AMH (anti-Mullerian hormone)
Diseases named in the same sentence as AMH in open-access papers (continued):
Sharing a sentence is not in itself a finding about the gene and the disease.
Azoospermia (8 papers, 2013 to 2024). Absence of any measurable level of sperm,whereby spermatozoa cannot be observed even after centrifugation of the semen pellet. "Patients with basal FSH > 20 IU/l, AMH < 0.1 ng/mL and severe male factors (azoospermia with testicular biopsy) were excluded." (PMID 35456190, 2022). "We then used real-time RT-PCR to quantitatively analyze the expression levels of AR, SOX9 and AMH in the 23 and 33 patients with obstructive azoospermia with normal spermaotgensis and SCOS, respectively." (PMID 24098470, 2013). "Although we only see limited evidence from meta-analysis, serum AMH does not appear to have diagnostic value as a stand-alone marker of persistent spermatogenesis in men with non-obstructive azoospermia." (PMID 24098470, 2013). "Subsequent studies proposed that the glycoprotein Anti-Müllerian hormone (AMH), produced by testicular Sertoli cells, could be a biomarker of azoospermia, as it was undetectable in SP of OA men and was present at very low levels in men with NOA, compared to fertile donors." (PMID 32987677, 2020). "These testiculopathic testes have thickened and hyalinized basal membranes that may prevent AMH from crossing the blood-testis barrier and entering circulation, perhaps explaining why serum AMH may not be a suitable prognostic marker in patients with non-obstructive azoospermia." (PMID 24098470, 2013).
lymphoma (8 papers, 2013 to 2024). A malignant (clonal) proliferation of B- lymphocytes or T- lymphocytes which involves the lymph nodes, bone marrow and/or extranodal sites. "The AMH level has been reported as a suitable marker of ovarian reserve in women treated for lymphoma, reflecting the gonadotoxicity of the drug regimen." (PMID 24312222, 2013). "In particular, in the study by Lekovich and colleagues women with lymphomas had lower baseline AMH levels and AFC when compared to healthy controls and women with a different type of malignancy; moreover, their oocyte retrieval was reduced with respect to controls after adjusting the results by age." (PMID 37370751, 2023). "A study in lymphoma patients showed significantly lower AMH levels than in the control group." (PMID 32185016, 2019). "Alternatively, higher concentrations of inflammatory and endothelial dysfunction markers among lymphoma patients including interleukin 6 are significantly correlated with decreased AMH concentrations as well as CVD risk, suggesting that AMH may also be linked with CVD through this pathway." (PMID 30766706, 2017). "The assessment of gonadal function after lymphoma treatment in females includes history of menses, hormonal evaluation of FSH, estradiol and AMH, and transvaginal ovarian ultrasound examination with AFC." (PMID 37766870, 2023). "In this context, patients treated with COPP, BEACOPP, MIME, or BEAM, compared to ABVD, had a lower antral follicle count, a lower level of AMH, and significantly higher FSH levels of >15; 6 of 26 lymphoma patients (23%) conceived, with 3 of them using ovarian tissue transplantation (OTT)." (PMID 34207634, 2021).
autoimmune disease (7 papers, 2019 to 2025). A disorder resulting from loss of function or tissue destruction of an organ or multiple organs, arising from humoral or cellular immune responses of the individual to their own tissue constituents. "Anti-Mullerian hormone (AMH) is considered a reliable tool in patients with other autoimmune diseases for recognition and risk assessment of developing POI." (PMID 33807517, 2021). "Reduced AMH levels in patients with systemic sclerosis highlight the intersection between autoimmune disease and reproductive health." (PMID 39320461, 2024). "Anti-Mullerian hormone (AMH) is considered a reliable tool for recognition and risk assessment of developing POF in patients with other autoimmune diseases." (PMID 37752372, 2024). "Hence, several studies have analyzed serum AMH levels to evaluate FOR in women with autoimmune diseases." (PMID 32770239, 2020). "Overall, these recent studies suggest that the relationship between autoimmune diseases and diminished FOR, as assessed by AMH, remains inconsistent." (PMID 32770239, 2020). "Another marker of low ovarian reserve, Anti-Mullerian hormone (AMH), has been found to be decreased in reproductive-aged women with other autoimmune diseases and does not fluctuate with menstrual cycles as FSH and LH levels do." (PMID 31010259, 2019).
depression (7 papers, 2022 to 2025). "The examination how changes in specific hormone levels (e.g., estradiol, progesterone, FSH, AMH) across reproductive aging is also necessary to better understand the mechanisms contributing to increased risk for depression and PTSD during this reproductive stage." (PMID 39803367, 2024). "The levels of E2 (p < 0.05) and AMH (p < 0.01) were significantly decreased in depression-like mice." (PMID 36158217, 2022). "Parent education (Portion Sum of Squares (SS) = 11.4%) followed by AMH (Portion SS = 10.9%) and waist-hip-ratio (WHR) (Portion SS = 9.2%) were the most important variables in predicting depression." (PMID 40575266, 2025).
fibroids (7 papers, 2014 to 2023). "A randomized comparison measuring AMH levels following UAE for fibroids indicated that AMH level, which is a measure of ovarian reserve, is decreased when compared to surgical hysterectomy." (PMID 26523290, 2015). "Compared with a single fibroid, two fibroids and AMH could significantly influence the clinical pregnancy rate." (PMID 36835936, 2023). "The surgical procedure of incising the uterus and removing leiomyoma tissue might interrupt blood flow to the ovaries, resulting in a temporary decrease in AMH level." (PMID 37972094, 2023). "The randomized EMMY trial compared FSH and AMH levels after hysterectomy and UAE in premenopausal women with symptomatic fibroids within a 2-year follow-up." (PMID 29859107, 2018).
Hypergonadotropic hypogonadism (7 papers, 2017 to 2024). Reduced function of the gonads (testes in males or ovaries in females) associated with excess pituitary gonadotropin secretion and resulting in delayed sexual development and growth delay. "Hormonal work-up in female subjects IV-1 and IV-5 revealed hypergonadotropic hypogonadism and very low AMH levels." (PMID 36769638, 2023).
MRKH syndrome (7 papers, 2007 to 2023). "AMH signal transduction induces the degradation of MDs, and has been long implicated in MRKH syndrome." (PMID 26075712, 2015). "As a third group of genes, AMH and its receptor have been regarded as causative factors in MRKH syndrome as AMH initiates MD regression in the 6th gestational week." (PMID 21619687, 2011). "Besides, there is even the assumption that activator mutations in the gene for anti-Müllerian hormone (AMH) or in its receptor (AMHRII) may be considered as potential causes of the MRKH syndrome." (PMID 23431465, 2013). "A number of studies aimed to investigate the genetic causes of MRKH syndrome, focusing on CNVs and candidate genes involving TBX6, AMH, LHX1, WNT, and HOX." (PMID 37789575, 2023). "As the malformation manifests early during embryonic development, associated genes such as HOX, WNT, and those encoding anti-Müllerian hormone (AMH) and its receptor have been proposed to be key for MRKH syndrome." (PMID 33072755, 2020). "The discovery of a four-gene epistatic effect (AMH, PBX1, WNT7A and WNT9B) in MRKH syndrome provides novel information for the elucidation of the genetic mechanism underlying the etiology of MRKH syndrome." (PMID 26075712, 2015). "Numerous genes exhibiting a wide range of activity during MD development, such as PBX1, HOX family genes, WNT family genes and ant-Müllerian hormone (AMH), have been suggested as candidates for MRKH syndrome based on phenotypes that have been observed in mutant mice." (PMID 26075712, 2015). "One of the first hypotheses for the underlying cause of MRKH syndrome was an activating mutation of either the gene for the AMH receptor (AMHR), resulting in the inappropriate production of AMH, or the receptor itself." (PMID 21619687, 2011). "Aberrant expression of anti-Müllerian hormone (AMH) or its receptor, both involved in Müllerian duct regression was hypothesized as a cause of MRKH syndrome; however, this theory was later discounted as a result of contradictory findings from a study of 32 patients." (PMID 17359527, 2007). "Multifactor dimensionality reduction (MDR) analysis revealed novel dimensional epistatic four-gene effects (AMH, PBX1, WNT7A and WNT9B) in MRKH syndrome." (PMID 26075712, 2015). "The best four-way interaction model indicated by MDR analysis supported the following novel and bold assumption that the dimensional interactions of AMH, PBX1, WNT7A and WNT9B may play a role in the etiology of MRKH syndrome during MD development." (PMID 26075712, 2015). "Notably, we found a novel dimensional epistatic four-gene effect (AMH, PBX1, WNT7A and WNT9B) in MRKH syndrome, providing novel data to contribute to the elucidation of the genetic mechanisms underlying its multifactorial etiology." (PMID 26075712, 2015). "Previous studies have screened the entire AMH gene and its receptor for DNA sequence variations and have measured this hormone levels in MRKH syndrome patients, reporting negative results." (PMID 26075712, 2015). "Nevertheless, mutation analyses of the AMH gene did not support a link between the MRKH syndrome and AMH at the genome level." (PMID 21619687, 2011). "Mutation analyses of the AMH gene, however, did not support a link between MRKH syndrome and AMH yet." (PMID 21619687, 2011).
Oligomenorrhea (7 papers, 2015 to 2026). Infrequent menses (less than 6 per year or more than 35 days between cycles). "Oligomenorrhea in the previous menstrual period might cause AMH levels to increase by 3.826 units after LOD (P-value < 0.001)." (PMID 36042475, 2022). "The AMH criterion was fulfilled by 54 (32%) women with oligomenorrhea followed by AFC criterion, 50(%), and FSH level criterion, 47 (%)." (PMID 29201666, 2017).
anorchia (6 papers, 2016 to 2024). "Indeed, basal serum AMH proves to be more informative than testosterone post-hCG both in boys with abdominal testes and in boys with anorchia." (PMID 38501100, 2024). "The normal male appearance at birth with no intersexuality features and no Müllerian ducts derivatives prove that functional AMH (Anti-Müllerian hormone) activity had been present during foetal life and make congenital bilateral anorchia unlikely." (PMID 26909487, 2016). "None of the patients presented undetectable AMH, which is highly suggestive of anorchia." (PMID 39797156, 2024). "The predictive value of detectable serum AMH for the presence of testes was 98% and that of undetectable serum AMH for anorchia was 92%; the only false negative result was observed in a boy with PMDS due to an AMH mutation who had testes but serum AMH was undetectable." (PMID 38501100, 2024). "In contrast, boys with anorchia present a typical hormonal profile during minipuberty (and childhood) with very high LH and FSH levels and low or undetectable levels of testosterone, inhibin B and AMH—regarded as the most specific marker of existing testicular tissue." (PMID 31396156, 2019). "The endocrine tests suggested absent testicular function (low AMH, low to undetectable testosterone, high FSH and luteinizing hormone) so acquired bilateral anorchia was considered." (PMID 26909487, 2016).
adenomyosis (5 papers, 2021 to 2024). The growth of endometrial tissue inside the muscular wall of the uterine corpus. "The aim of this review is to compare the AMH levels in serum before and after adenomyosis treatment." (PMID 36120472, 2022). "The aim of this mini-review is to illustrate the potential prognostic and therapeutic role of AMH in adenomyosis." (PMID 36120472, 2022). "The aim of this mini-review is to illustrate the potential prognostic and therapeutic role of AMH in adenomyosis, considering the scientific works published in the last 5 years." (PMID 36120472, 2022). "Our study tried to summarize the latest evidences on the correlation between AMH and adenomyosis: the number of scientific works published in the last five years are low, but the results are promising." (PMID 36120472, 2022). "The relationship between adenomyosis and AMH concentration remains uncertain." (PMID 38562412, 2024). "These predictors included maternal physiology (maternal age at oocyte retrieval and serum AMH level), uterine factor (adenomyosis), and embryo assessment (number of fertilized embryos, blastocyst morphology, blastulation day, blastocyst re-expansion speed, and presence of embryo string)." (PMID 38075065, 2023). "The correlation between anti-Mullerian hormone (AMH) expression and adenomyosis is unclear." (PMID 36120472, 2022). "The available evidence shows an unclear relationship between adenomyosis and AMH." (PMID 36120472, 2022). "Furthermore, a molecular pathology study found that in adenomyotic tissue there is a higher expression of AMHRII, thus we can speculate a possible use, in the future, of AMH as a therapy for adenomyosis." (PMID 36120472, 2022). "Patients with concurrent adenomyosis also had a more pronounced decrease in AMH levels than did those without adenomyosis (p=0.034)." (PMID 38562412, 2024). "Patients with adenomyosis had lower pretreatment AMH levels and a greater posttreatment decline, but their median age was higher than that of patients without adenomyosis, suggesting potential age-related bias." (PMID 38562412, 2024). "Probably, women with adenomyosis have lower levels of AMH and the surgical treatment (adenomyomectomy, HIFU) does not alter this characteristic, therefore in all of them, ovarian function is not influenced." (PMID 36120472, 2022). "Probably, women with adenomyosis have lower levels of AMH and the surgical treatment (adenomyomectomy, HIFU) does not alter this characteristic, so in all likelihood ovarian function is not influenced." (PMID 36120472, 2022). "Our mini-review showed that surgical treatment of adenomyosis (adenomyomectomy, HIFU) does not influence AMH levels and thus has a negligible role on ovarian function." (PMID 36120472, 2022). "Additionally, patients with coexisting adenomyosis had a reduced AMH concentration, with a median of 2.45 (IQR 2.14) ng/ml, compared to those without adenomyosis, who had a median AMH concentration of 3.19 (IQR 3.32) ng/ml (p=0.004)." (PMID 38562412, 2024).
androgen insensitivity syndrome (5 papers, 2009 to 2024). Androgen insensitivity syndrome (AIS) is a disorder of sex development (DSD) characterized by the presence of female external genitalia, ambiguous genitalia or variable defects in virilization in a 46,XY individual with absent or partial responsiveness to age-appropriate levels of androgens. "AMH is low in gonadal dysgenesis, partial androgen insensitivity syndrome and when there are mutations in the gene affecting AMH production." (PMID 21274298, 2009). "Basal AMH levels are high in androgen insensitivity syndrome." (PMID 21274298, 2009). "Accordingly, AMH levels do not decrease at pubertal age in mice with disrupted androgen signalling and in humans with defective androgen synthesis or with a complete androgen insensitivity syndrome (CAIS) due to AR mutations." (PMID 32934281, 2020). "In adult patients with Sertoli-cells-only syndrome (SCOS) and androgen insensitivity syndrome (AIS), high level of AMH expression is detected in Sertoli cells due to defect of androgen/AR signaling." (PMID 24098470, 2013). "In conditions like complete androgen insensitivity syndrome (CAIS), AMH downregulation does not occur and AMH increases at puberty, due in part to follicle-stimulating hormone (FSH) effect." (PMID 32934281, 2020). "Similarly, immunohistochemical staining revealed high AMH expression in male mice lacking AR in their Sertoli cells, and human patients with androgen insensitivity syndrome (AIS) showed abnormally high levels of AMH." (PMID 24098470, 2013).
endometrial cancer (5 papers, 2013 to 2025). Primary or metastatic malignant neoplasm involving the endometrium (mucous membrane that lines the endometrial cavity). "Until now, data concerning the association between AMH and risks of endometrial cancer is still ambiguous." (PMID 30884769, 2019). "AMH has been shown to inhibit the growth of human endometrial cancer cell lines with high AMHR2 expression by increasing cell cycle arrest and apoptosis." (PMID 39230026, 2024). "In the endometrial carcinoma cell line AN3CA, MIS/AMH reduces cell viability by regulating pathways associated with cell cycle arrest, apoptosis, and Wnt signaling." (PMID 34539902, 2021). "High circulating AMH levels are supposed to be proportional to the protection effect against the development of endometrial cancer." (PMID 30884769, 2019). "The aim of the study was to assess whether the tissue of pre-cancerous states of endometrium (PCS) and various histopathologic types of endometrial cancer (EC) exhibit the presence of AMH." (PMID 30884769, 2019). "In fact, AMH exerts an inhibitory effect by inducing apoptosis and cell cycle arrest in AMHRII positive endometrial cancer cell lines." (PMID 30884769, 2019).
Menstrual disorder (5 papers, 2018 to 2024). Category of disorders related to menstruation. "The current study aimed to assess the menstrual disorder and the AMH, TSH, TPO, and prolactin levels in female patients with COVID-19." (PMID 39906086, 2024). "This study aimed to investigate the effect of the COVID-19 virus on menstrual disorders, anti-Mullerian hormone (AMH), thyroid peroxidase (TPO), thyroid stimulating hormone (TSH), and prolactin levels in women with COVID-19 disease." (PMID 39906086, 2024). "The study demonstrates a relationship between menstrual disorders and low levels of vitamin D, which may be related to AMH, insulin, and androgen or which could perhaps involve a yet-to-be-identified pathway." (PMID 30423869, 2018).
systemic lupus erythematosus (5 papers, 2020 to 2021). An autoimmune multi-organ disease typically associated with vasculopathy and autoantibody production. "This is in keeping with studies of other autoimmune conditions that have reported reduced AMH levels in women with Crohn’s disease or systemic lupus erythematosus compared to healthy controls." (PMID 32399364, 2020).
abortion (4 papers, 2017 to 2023). the ending of pregnancy by removing a fetus or embryo before it can survive outside the uterus. "When AMH ≤ 3.1 ng/mL, AMH was negatively correlated with the occurrence of spontaneous abortion; the higher the AMH value, the lower the incidence of abortion." (PMID 34059771, 2021). "However, when AMH > 3.1 ng/mL, according to the analysis of the segmented threshold effect based on the smooth points curve, the probability of spontaneous abortion and AMH was not statistically significant before and after the turning point of 11.6 ng/mL." (PMID 34059771, 2021). "Similarly, we found that AMH was also an independent predictor of spontaneous abortion through a smooth fitting curve, but there was still a nonlinear relationship." (PMID 34059771, 2021).
acne (4 papers, 2017 to 2025). An inflammatory process of the sebaceous glands which is characterized by comedones, nodules, papules and/or pustules on the skin. "In women who reported reducing their consumption of red and fatty meat less than 6 months ago, higher average A4, AMH and acne (p < 0.05) were observed compared to those who did not implement such restrictions." (PMID 40283538, 2025).